IL18 (interleukin 18)
Diseases named in the same sentence as IL18 in open-access papers (continued):
Sharing a sentence is not in itself a finding about the gene and the disease.
colitis (continued). "A recent study has reported that IL-18Rα-deficient CD4+ T cells induced comparable intestinal pathology to WT CD4+T cells, concluding that IL-18-dependent cytokine induced activation of these cells is not critical for the development of T-cell-induced colitis." (PMID 31379813, 2019). "Thus, we hypothesis that RAI16 knockout could suppress the secretion of IL-18 and the expression of IL-22 binding protein (IL-22BP) in intestinal epithelial cells, consequently downregulate the secretion of STAT3-dependent Reg3γ and Reg3β, all together, which induces dysbiosis linked colitis." (PMID 31862898, 2019). "Other studies of colitis have shown a lack of IL-18 results in more severe disease, and the administration of IL-18 can reverse the phenotype." (PMID 31380382, 2019). "While anti-IL-18 induced by IL-18 vaccine D could partially block IL-18-induced IFN-γ secretion in vitro and also improve murine colitis in vivo." (PMID 31428451, 2019). "Surprisingly, the results from these studies indicate that IL-18, but not IL-1β, plays a major role in suppressing colitis." (PMID 28955343, 2017). "We found that the levels of active IL-1β and IL-18, which are induced by the inflammasome, but not IL-6 and TNF-α, were associated with increased FLC and inflammatory damage in colitis tissues or tumor formation in AOM/ DSS-induced CAC." (PMID 28701727, 2017). "In particular, treatment with two specific MALT1 inhibitors, MI-2 and mepazine, dose-dependently attenuated the symptoms of colitis in mice through a decrease in protein and mRNA levels of colonic TNF, IL-1β, IL-6, IL-18, IL-17A, and IFN-γ pro-inflammatory cytokines." (PMID 28179906, 2017). "In this study, exogenous IL-1β reduced expression of colonic Th2 cytokines (IL-4 and IL-13) and improved OXA-induced colitis, while exogenous IL-18 also reduced severity of the colitis but without affecting expression of Th2 cytokines." (PMID 27966619, 2016). "Either exogenous IL-1β or IL-18 ameliorated the colitis with or without reduction in Th2 cytokine expression, respectively." (PMID 27966619, 2016). "Although detailed mechanism behind the downregulation of IL-18 remains unclear, the dynamics of IL-18 expression may differ among different inflammatory conditions, and this downregulation may lead to enhancement of inflammation in OXA-induced colitis." (PMID 27966619, 2016). "Modulation of NLRP3 in the gut epithelium by high-fiber feeding has been suggested to contribute to intestinal homeostasis and protection from colitis through maintenance of a healthy microbiota and due to SCFA-mediated sensing by G-protein-coupled receptors GPR43 and GPR109A and IL-18 release." (PMID 26925061, 2016). "To determine whether decreased IL-18 production was also responsible for the excessive DSS-induced colon damage in Casp11−/− mice, we administered rIL-18 i.p. to mice during DSS-induced colitis." (PMID 25548224, 2015). "Both IL-22 and IL-18 have important roles in IEC proliferation and epithelial barrier repair; therefore, their decreased levels in Casp11−/− mice during DSS colitis are consistent with the increased barrier permeability and severe mucosal damage observed in these mice." (PMID 25548224, 2015). "The relative mRNA expression of pro-inflammatory factors (IL-1β, TNF-α, and IL-18) was significantly increased in the DSS group compared to the CON group (p < 0.05), indicating a disruption in the balance of inflammatory factors and impaired intestinal immunity in the colitis mice." (PMID 41227621, 2025). "However, concomitant ablation of IL-18 and T-TNF did not influence recovery of colitis, suggesting that IL-18 is dispensable in this experimental setting." (PMID 35383266, 2022). "In the dextran sulfate sodium (DSS)-induced mouse colitis model, metformin, an AMPK activator, could significantly inhibit the activation of IKK induced by DSS, thereby down-regulating the expression of the inflammatory factor IL-18." (PMID 34628369, 2021).
colitis (continued). "Studies on colitis induced-mice models lacking Nlrp6 evidenced that IL-18 was less expressed, mucus secretion in goblet cells was dysregulated and the overall clearance of bacterial pathogens was impaired, leading to alterations in the quantity and composition of the microbiota." (PMID 32659925, 2020). "Importantly, the inflammasomes effector IL-18, but not IL-1β, plays a pivotal role in suppressing colitis." (PMID 30609850, 2019). "We showed that exogenous IL-1β, as well as exogenous IL-18, improved OXA-induced colitis in WT mice and prevented worsening of colitis in NLRP3−/− mice, strongly suggesting that the NLRP3 inflammasome-derived IL-1β may have an inhibitory effect on OXA-induced colitis." (PMID 27966619, 2016). "Thus, although the mechanism of MUC2 induction by IL-18 remains unknown, this stimulatory effect of IL-18 on MUC2 expression via CDX-2 upregulation seems to contribute to alleviation of colitis." (PMID 27966619, 2016). "Such differential licensing may contribute to the selective production of IL-18, but not IL-1β, by epithelial cells during dextran induced colitis." (PMID 23028835, 2012). "In addition, overexpression of miR‐378a in UmC‐MSC‐EVs suppresses the secretion of IL‐18, IL‐1β and caspase‐1 cleavage target by reducing NLRP3 inflammasome activity, preventing pyroptosis, and thus increasing cell survival in dextran sulphate sodium (DSS)‐induced colitis mice." (PMID 39488745, 2024). "However, antibody-mediated IL-18 neutralization did not rescue Ccr8−/− from severe intestinal pathology indicating that excessive IL-18 signaling is not a main driver of colitis in this strain." (PMID 33613532, 2020). "However, the genetic deletion of IL-18 from mice has opposing effects in models of colitis, depending on whether it is produced by hematopoietic or non-hematopoietic cells." (PMID 30214011, 2018). "In PBS-treated males, colitis resulted in markedly elevated IL-6 and no significant changes in PST, IL-22, and IL-18 levels compared to in the corresponding non-colitic PBS-treated mice." (PMID 39684467, 2024). "However, the different expression of IL‐18 might also contribute to “conflicting” observations regarding the role of IL‐18 in NEC (occurring in the ileum) as opposed to its role in DSS‐induced colitis (most severe in the distal colon)." (PMID 30515917, 2019). "However, we believe that contributions of pro-IL-1β and pro-IL-18 downregulation to colitis are none or negligible because impact of Rev-erbα on inflammasome activation (i.e., activation of caspase-1 and maturation of IL-1β) and experimental colitis is highly Nlrp3-dependent." (PMID 30315268, 2018). "Induction of colitis decreased MUC2 expression, which was reversed by administration of IL-18, but not IL-1β." (PMID 27966619, 2016). "Models of experimental colitis have shown that macrophages promote crypt proliferation and that NLRP3 inflammasome production of IL-18 (not IL-1β) is required for epithelial protection." (PMID 24312491, 2013). "To more specifically evaluate NLRC4V341A effects in a gastrointestinal infection model leading to IL-18 production from IECs, we infected NLRC4V341A/V341A mice with C. rodentium, as NLRC4 responses in non-hematopoietic cells were shown to restrict colitis induced by this enteropathogen." (PMID 38090573, 2023). "Remarkably, data are claiming that the compound MCC950 can significantly suppress the release of proinflammatory cytokines IL-1β, IL-18, and IL1-α, contribute to inflammatory effects resulting from canonical and non-canonical NLRP3 inflammasome activation in colitis." (PMID 30873162, 2019). "In the present study, although anti-IL-18 induced by IL-18 vaccine A could partially block IL-18-induced IFN-γ secretion in vitro, it did not improve murine colitis in vivo." (PMID 31428451, 2019).
Sepsis (265 papers, 2008 to 2026). Sepsis is defined as life-threatening organ dysfunction caused by a dysregulated host response to infection. "In experimental models, IL-18 has been linked to gut barrier dysruption, increased bacteremia, and sepsis-related mortality." (PMID 40510342, 2025). "Compared to traditional markers like CRP, PCT, and white blood cell count (WBC), IL-18 has demonstrated better diagnostic discrimination for sepsis and septic shock." (PMID 40510342, 2025). "In sepsis, high levels of proinflammatory cytokines (i.e., IL-6, IL-8, IL-18, and IL-1β) have been associated with higher mortality, a similar correlation in IE patients can be assumed." (PMID 41152385, 2025). "Our ROC analysis revealed that RIPK-1 and IL-18 demonstrated good diagnostic accuracy for sepsis within 24 h of ICU admission—suggesting strong potential as early biomarkers of disease severity." (PMID 40722817, 2025). "Other ILs, such as IL-8, IL-12, IL-18, and IL-17, contributed to neutrophil recruitment, Th1/Th17 activation, organ-specific injury, and sepsis susceptibility." (PMID 41300951, 2025). "Elevated IL-18 levels have been consistently associated with sepsis severity and poorer outcomes in critically ill patients, outperforming conventional markers like procalcitonin and CRP in diagnostic utility in some studies." (PMID 40722817, 2025). "One post-hoc analysis of an RCT examined the effect of simvastatin in sepsis-induced ARDS in patients with high baseline IL-18, which was associated with a higher survival probability (39% vs. 24%, n = 511)." (PMID 38807151, 2024). "In a randomized controlled trial, plasma IL-18 levels were also discovered to be associated with the mortality in sepsis-induced ARDS." (PMID 38035100, 2023). "IL-18 in patients with septic ARDS were significantly higher than patients with sepsis alone, demonstrating that IL-18 in sepsis are key cytokines causing lung injury." (PMID 38035100, 2023). "Interleukin (IL)-18 is a marker of inflammasome activation, and high baseline plasma IL-18 is associated with increased mortality in patients with sepsis-induced ARDS." (PMID 35672834, 2022). "The expression of the TXNIP-NLRP3 complex in monocyte-derived exosomes caused sepsis-related cardiovascular inflammation and myocardial dysfunction by promoting the activation of IL-1β and Interleukin-18 (IL-18) in macrophages." (PMID 36579343, 2022). "The production of IL-6, TNFα, IL-18, and IL-1 pro-inflammatory cytokines along with IL-10 (anti-inflammatory cytokine) is a hallmark response to sepsis." (PMID 36439175, 2022). "Sepsis was independently associated with higher serum IL-18 and TNF levels in two time-point GEE models (53–723, p = 0.023 and 0.3–64, p = 0.048, respectively)." (PMID 35054259, 2021). "The relationship between serum ACLY and IL‐18 and underlying mechanisms involved in the pathophysiology of sepsis need further study in the future." (PMID 33378581, 2021). "Although we did not observe a significant increase of cytokines at the end of SBT, we demonstrated that sepsis was independently associated with higher serum IL-18 and TNF levels at two time points (baseline, 30 min)." (PMID 35054259, 2021). "It is well documented that increased IL-18 levels are associated with worse severity and worse outcome of sepsis." (PMID 35054259, 2021). "Sepsis was independently associated with higher serum levels of IL-18 and TNF at two time points (before and at the end of SBT)." (PMID 35054259, 2021). "Serum inflammatory mediators associated with sepsis (IL-18, IL-18BP, TNF) were determined and correlated with the outcome of SBT." (PMID 35054259, 2021). "As an important mode of cell death in early sepsis, pyroptosis is likely to be a major cause of the immune storm because of its concomitant release of the proinflammatory factors IL-1β and IL-18." (PMID 32851082, 2020).
Sepsis (continued). "Renal and pulmonary expression of NLRP3 and Caspase 1 were unchanged in response to sepsis, although tissue levels of inflammasome-associated cytokines IL-1β and IL-18 did increase in after CLP." (PMID 32555710, 2020). "Polymorphisms in the IL-18 gene have been studied for association with inflammatory conditions such as type 1 diabetes and sepsis." (PMID 19178691, 2009). "We analyzed whether the polymorphism was correlated with the cytokine expression of IL1β, IFNα2, IFNγ, TNF-α, IL-33, IL12p70, MCP-1, IL-6, IL-10, IL-17a, IL-18, or IL-23 to further investigate the effect of the polymorphism in sepsis patients." (PMID 38338680, 2024). "Synthesizing previously study results with the findings of this study, rs17525809 (T253C) may be protective in severe infections such as pneumonia and early sepsis inflammasome associated illness by attenuating cytokine levels such as IL-1β and IL-18." (PMID 38966639, 2024). "For example, over-released IL-18 caused diabetic retinopathy by increasing retinal vascular permeability, and IL-1β could destroy vascular integrity during sepsis-induced lung injury through suppressing VE-cadherin expression in lung endothelial cell." (PMID 36923408, 2023). "In addition, the IL-1 gene cluster SNP genotypes containing minor alleles and IL-18 rs187238G positive genotypes were found as associated with risk of severe complications such as sepsis, septic shock, acute respiratory distress syndrome and coma." (PMID 36551320, 2022). "In both control and OVR females, sepsis increased the myocardial expression of genes encoding protein associated to inflammation, interleukin-6 (IL-6), IL-10 and IL-18, to cell cycle and survival, Janus Kinase 2 (JAK2) and signal transducer and activator of transcription 3 (STAT3)." (PMID 35322092, 2022). "Moreover, there is evidence that underlines as IL-18 is involved in injury induction in different organs such as lung, liver, and intestine and as its levels correlate with disease severity in sepsis, lupus erythematous and heart failure." (PMID 36287942, 2022). "Our results demonstrate that HBP could be a useful, novel biomarker that could be used as an alternative or in conjunction with IL-18 for improved diagnostic accuracy to distinguish between sepsis and AOSD, as well as active and inactive AOSD." (PMID 33868298, 2021). "Moreover, a pro-inflammatory cytokine, IL-18, has also been found to be associated with sepsis by increasing endothelial permeability." (PMID 28929009, 2017). "Sepsis caused by B. pseudomallei is characterized by a markedly proinflammatory cytokine profile; in the current cohort of patients we have demonstrated increased plasma concentrations of IL-6, IL-8 and IL-18 when compared to controls." (PMID 20169062, 2010). "Finally, the findings were not validated in an external cohort, and larger, prospective, and multicenter studies with longitudinal biomarker profiling and standardized treatment protocols are needed to confirm the diagnostic and prognostic utility of IL-18 and other cytokines in sepsis." (PMID 40510342, 2025). "In this context, recent bioinformatic studies have identified several genes involved in IL-18 signalling and cell development as potential diagnostic biomarkers in sepsis, providing additional layers of molecular information that may complement cytokine-based profiling." (PMID 41300951, 2025). "Also, biochemical markers are associated with the alterations in IL18 levels during sepsis." (PMID 30850654, 2019). "Sepsis patients with CG/GG genotypes had significantly higher IL-18 levels than those with the CC genotype." (PMID 42311758, 2026). "In fact, simultaneous blockade of IL-1 and IL-18 has been shown to confer full protection in murine models of sepsis induced by LPS or cecal ligation and puncture." (PMID 40510342, 2025).
Sepsis (continued). "Material and Methods: We analyzed recent clinical and experimental studies focusing on the most studied ILs—including IL-1, IL-6, IL-10, IL-8, IL-12, IL-18, and IL-17—in the pathophysiology of sepsis." (PMID 41300951, 2025). "Mortality, AKI, and acute respiratory distress syndrome (ARDS) were correlated with IL-18 levels in both groups of sepsis." (PMID 40429966, 2025). "Pro-inflammatory cytokines like IL-6, MCP-1, and IL-18 were elevated, as was the anti-inflammatory IL-10 in both sepsis cohorts compared to healthy controls." (PMID 40510342, 2025). "One study showed that IL-18, alongside KIM-1 and the renal resistive index, are good predictors for developing AKI in patients with sepsis, with IL-18 demonstrating the highest sensitivity." (PMID 40429966, 2025). "These inconsistencies underscore the heterogeneity of IL-18 responses in sepsis and suggest a need for larger, more stratified studies." (PMID 40510342, 2025). "Our study also demonstrated substantially elevated levels of IL-1β and IL-18 in critically ill patients—including those with sepsis—compared to healthy adult and pediatric controls." (PMID 40722817, 2025). "We found that Areg, Egfr, Il1b, and Il18 were highly expressed in monocytes of patients with severe sepsis compared with those in patients with general sepsis or healthy controls." (PMID 40292295, 2025). "In the context of severe sepsis and septic shock, the excessive release of IL-1, IL-18, and IL-33 leads to cytokine storm characterized by uncontrolled inflammation and widespread tissue damage." (PMID 41300951, 2025). "The multivariate regression analysis showed that IL‐15 and IL‐18 contributed to the differentiation between sepsis and non‐sepsis patients." (PMID 40041474, 2025). "In patients with acute-on-chronic liver failure (ACLF) complicated with sepsis, serum IL-18 is significantly raised when compared to patients with ACLF with or without systemic inflammation." (PMID 40429966, 2025). "Markers of an IFNγ response were higher in sepsis than in healthy patients, including IL-18 (p=0.02) which increases IFNγ production and MIG (p<0.0001), an IFNγ inducible chemockine." (PMID 39935482, 2025). "Comparative analysis across diagnostic categories revealed that patients with sepsis exhibited significantly elevated levels of RIPK-1, IL-1β, and IL-18, along with reduced caspase-8 levels, relative to patients with SIRS or cardiac conditions." (PMID 40722817, 2025). "In conclusion, our findings add to the growing body of evidence supporting IL-18 as a promising biomarker in sepsis." (PMID 40510342, 2025). "The value of IL-18 as a mortality predictor in sepsis is disputed, as there are varying results from clinical and in vitro studies." (PMID 40429966, 2025). "The authors of this study also noted that the five patients with signs of systemic inflammation and increasing IL-18 concentrations within 24 h of admission also developed sepsis." (PMID 40429966, 2025). "In this context, the IL-18/TNF-α ratio has emerged as a robust predictor of clinical severity in sepsis, further underscoring IL-18 as both a biomarker and a potential therapeutic target." (PMID 41300951, 2025). "The pathophysiology of sepsis is characterized by hyperactive and dysregulated endogenous inflammatory mediators, including IL-1β, IL-18, and TNF-α." (PMID 38584827, 2024). "A significant upregulation of circMAPK1 was observed in patients suffering from sepsis-induced lung injury, along with elevated serum levels of the inflammatory cytokines IL-1β and IL-18." (PMID 39300342, 2024). "We opted for a ready-made reagent kit for cytokine analysis, which led to the omission of several well-recognized cytokines associated with sepsis progression, such as CXCL-1, IL-18, IL-26, and IL-27." (PMID 38707899, 2024). "The correlation between the occurrence of sepsis and the release of IL-18 as well as the rate of monocyte pyroptosis has been established." (PMID 39267971, 2024).